SERPINA3 (serpin family A member 3)
Description:
Although its physiological function is unclear, it can inhibit neutrophil cathepsin G and mast cell chymase, both of which can convert angiotensin-1 to the active angiotensin-2.
Synonyms: ACT; AACT; GIG24; GIG25
Tractability: Small molecule: it has a binding pocket of medium quality. Antibody: its Gene Ontology location is reachable by antibodies, with high confidence; UniProt places it where antibodies can reach, with medium confidence; UniProt predicts a signal peptide or a membrane-spanning region. PROTAC: its protein half-life has been measured.
Gene: Protein-coding gene on chromosome 14 (94,612,377 to 94,624,645, forward strand). Ensembl gene ENSG00000196136.
Subcellular location: Secreted
Pathways (Reactome):
Hemostasis: Platelet degranulation
Immune System: Neutrophil degranulation
Gene Ontology:
Molecular function: protein binding; DNA binding; serine-type endopeptidase inhibitor activity
Biological process: inflammatory response; maintenance of gastrointestinal epithelium; regulation of lipid metabolic process; response to cytokine
Cellular component: blood microparticle; extracellular exosome; extracellular matrix; extracellular region; azurophil granule lumen; nucleus; platelet alpha granule lumen; secretory granule lumen
Genetic constraint (gnomAD): Loss-of-function variants: 32 observed, 28.34 expected, observed/expected ratio (o/e) 1.13, 90% interval 0.85 to 1.52. The upper end of that interval is the gene's LOEUF score, 1.52, which puts it in group 6 of 6, group 1 being the genes least tolerant of losing a copy. Missense variants: 624 observed, 537.58 expected, observed/expected ratio (o/e) 1.16, 90% interval 1.09 to 1.24. Synonymous variants: 249 observed, 214.04 expected, observed/expected ratio (o/e) 1.16, 90% interval 1.05 to 1.29.
Homologues: Orthologues: chimpanzee SERPINA3 (97% identical), macaque SERPINA3 (89% identical), dog SERPINA3 (65% identical), rabbit SERPINA3 (63% identical), mouse Serpina3n (61% identical), mouse Serpina3m (61% identical), rat Serpina3a (61% identical), guinea pig SERPINA3 (60% identical), rat Serpina3a (60% identical), mouse Serpina3c (59% identical), pig SERPINA3-2 (58% identical), mouse Serpina3f (58% identical), and 10 more. Paralogues in human: SERPINA9 (45% identical), SERPINA5 (44% identical), SERPINA4 (44% identical), SERPINA6 (43% identical), SERPINA1 (43% identical), SERPINA7 (41% identical), SERPINA11 (40% identical), SERPINA12 (33% identical), SERPINB1 (32% identical), SERPINB9 (31% identical), SERPIND1 (31% identical), SERPINB6 (30% identical), and 24 more.
Diseases named in the same sentence as SERPINA3 in open-access papers:
SERPINA3 is named in the same sentence as 208 diseases in open-access papers, as found by Europe PMC text mining. Sharing a sentence is not in itself a finding about the gene and the disease. The quoted sentences say what the papers report.
COVID-19 (27 papers, 2021 to 2026). A disease caused by infection with severe acute respiratory syndrome coronavirus 2. "ROC curve analysis shows that SERPINA3 can distinguish influenza, COVID-19, mixed infection and healthy people; SAA1 can distinguish COVID-19, mixed infection and healthy people; SAA2 can distinguish influenza and healthy people." (PMID 40158620, 2026). "Several proteins linked to the acute phase response, such as CRP, SERPINA3, SAA1 and SAA2, have been shown to increase in the plasma of patients with severe COVID-19 using MS-based data-independent analysis." (PMID 40568587, 2025). "The primary aim of this study was to evaluate urinary SerpinA3 (uSerpinA3) excretion as a biomarker of kidney recovery at 90 days, and the mortality in patients with critical COVID-19 and AKI requiring kidney replacement therapy (KRT)." (PMID 40804924, 2025). "The inflammatory factors SAA2, SAA1, SERPINA1, and SERPINA3 are significantly upregulated proteins in the sera of the severe COVID-19 patients." (PMID 38638822, 2024). "It is more important to determine the regulation of other SerpinA molecules, specifically SerpinA3, which is a more potent CatG inhibitor and was found to be upregulated in critical COVID-19 patients." (PMID 39339444, 2024). "During the COVID-19 pandemic, several proteomics studies have shown increased SERPINA3 levels in COVID-19 related ARDS patients in contrast to healthy controls, which accords with our earlier findings." (PMID 37197655, 2023). "CRP and SERPINA3, which are considerably more concentrated in the plasma of SEVEREs, have already been pointed out as candidate predictors for worse outcomes in COVID-19." (PMID 36834989, 2023). "We found that the plasma levels of HP, LTA4H, S100A9, SAA1, SAA2, and SERPINA3 were significantly elevated in more severe COVID-19 conditions, exhibiting good clinical predictive value and promising applications." (PMID 37197655, 2023). "The validation study using MRM could specifically detect AGT, FGG, APOB, SERPING1, and SERPINA3 host peptides in COVID-19 severe patients." (PMID 33995121, 2021). "Therefore, SERPINA3 is a candidate target for the control of both sepsis and COVID-19." (PMID 36864027, 2023). "The observed increase in levels of SERPINA1 and SERPINA3 might therefore partly reflect the more stable, chemoattractant, pro-inflammatory cleaved forms, rather than the short-lived tissue-protective proteins in severe COVID-19." (PMID 34139154, 2021). "Many of these proteins, such as SERPINA3, ORM1 and ORM2, have been used to distinguish between mild and severe cases of COVID-19." (PMID 38965561, 2024). "A recent study revealed that SERPINF2 expression increases in serum levels of patients with COVID-19, along with several other SERPINs (SERPINA1 and SERPINA3)." (PMID 36690780, 2023). "In terms of relevance to COVID-19 vulnerability, SERPINB10, SERPINE1, and SERPINA3 paint very different pictures." (PMID 37987478, 2023). "The markers ORM1, ORM2, S100A9, CRP, AZGP1, CFI, SERPINA3/ACT, and LCP1/LPL were significantly increased in more severe COVID-19 conditions, whereas the levels of FETUB, CETP, and PI16 were significantly decreased." (PMID 35269564, 2022). "To determine whether SERPINA3, SAA1, and SAA2 can serve as biomarkers for influenza, COVID-19, and Mix, we classified the three genes." (PMID 40158620, 2026). "The ROC curve showed that SERPINA3 could only distinguish between influenza, COVID-19, Mix, and health; SAA1 could only distinguish between COVID-19, Mix, and health; and SAA2 could only distinguish between influenza and health." (PMID 40158620, 2026). "Validation of SERPINA3, SAA1, and SAA2 as biomarkers for influenza, COVID-19, and Mix." (PMID 40158620, 2026). "Although neither SerpinA3 levels in blood nor a different spectrum of COVID-19 patients were included in the present study, it is known that these factors are closely linked to systemic inflammatory states." (PMID 40804924, 2025).
COVID-19 (continued). "A cohort of 71 patients (20 controls, 19 with non-critical COVID-19, and 33 with critical COVID-19) was studied in India, and the authors found higher serum SerpinA3 in patients with critical COVID-19, as a surrogate of disease severity." (PMID 40804924, 2025). "Traditionally, CRP has been used as a systemic clinical marker of inflammation in COVID-19 and other diseases, although the SROC curves suggest that other acute phase proteins, such as ORM1, CRTAC1, SERPINA3, TF, and AHSG might perform better as biomarkers of inflammation." (PMID 37739942, 2023). "Patient abundance of SERPINA3/A1AC, by contrast, is proposed to be very important for COVID-19 outcomes, but the relationship is directly analogous to trends for asthmatics, such that A1AC deficiency could be considered a major risk factor for both allergic asthma and severe viral infections." (PMID 37987478, 2023). "Moreover, most acute phase proteins, such as SAA1, SAA2, SAA4, CRP, SERPINA3, and SAP/APCS, which were increased in severe COVID-19 patients were not changed in our CoronaVac immunized samples." (PMID 35686122, 2022).
Alzheimer disease (26 papers, 2008 to 2025). A progressive, neurodegenerative disease characterized by loss of function and death of nerve cells in several areas of the brain leading to loss of cognitive function such as memory and language. "Using the “rms” package (version 6.2-0) in R (version 4.0.2), a nomogram model based on the 3 specific genes (CARTPT, EPHA5, and SERPINA3) was constructed to predict the risk of Alzheimer's disease (GSE122063)." (PMID 35996379, 2022). "Variations in human SERPINA3 sequence have been implicated in Alzheimer's disease, and deficiency of this protein has been associated with liver disease." (PMID 27247960, 2016). "The brain disease most strongly associated with the SerpinA3 gene is Alzheimer’s disease." (PMID 39062058, 2024). "Dysregulation of SERPINA3 has been reported to be associated with Alzheimer's disease." (PMID 37006491, 2023). "Network member Serpina3 has been directly linked to Alzheimer’s Disease (AD)." (PMID 38201293, 2023). "SERPINA3 dysregulation has been associated with Alzheimer’s disease (AD) and prion diseases." (PMID 35416570, 2022). "Elevated SERPINA3 levels have been found in cerebrospinal fluid of patients with Alzheimer’s disease, correlating with disease severity." (PMID 40157917, 2025). "Relatively consistent, the expression of SerpinA3N or SerpinA3 was upregulated in aging mice and mice with pineal inflammation, diabetes, traumatic brain injury, Alzheimer's disease, aneurysmal subarachnoid hemorrhage, glioma, colon cancer and other diseases." (PMID 37422673, 2023). "Elevated levels of SERPINA3 have been observed in heart failure and neurological diseases such as Alzheimer’s disease or Creutzfeldt–Jakob disease." (PMID 36672665, 2023). "Extensive research has been performed on the role of SERPINA3 in pathological changes in Alzheimer’s disease (AD)." (PMID 36672665, 2023). "SERPINA3/SerpinA3n marked dysregulation in prion and Alzheimer’s diseases, and its effect on the prion accumulation process, suggests its consideration as a potential therapeutic target." (PMID 35416570, 2022). "It was reported that SERPINA3 contributes to a wide range of diseases, such as chronic obstructive pulmonary disease, Parkinson's disease, Alzheimer's disease, and cancer." (PMID 34957248, 2021). "Existing data show that SERPINA3 is involved in the pathogenesis of chronic obstructive pulmonary disease, Parkinson's disease, Alzheimer's disease, and cancer." (PMID 34957248, 2021). "Molecular chaperon SERPINA3 colocalizes with accumulated amyloid peptide in Alzheimer’s disease (AD) patient’s brain." (PMID 33662018, 2021). "Alpha-1-antichymotrypsin (SERPINA3) is present in senile plaques and accelerates the formation of Aβ fibers associated with Alzheimer's disease (AD)." (PMID 32602849, 2020). "SERPINA3, which is commonly highly expressed in the brain tissue of Alzheimer’s disease patients, is essentially a serine protease inhibitor that attenuates neuroinflammation and cellular damage by inhibiting the activity of histone G as well as other inflammation-related enzymes." (PMID 40076571, 2025). "Recently, SerpinA3N/SerpinA3 has been found to be significantly upregulated in neurological diseases, such as traumatic brain injury, Alzheimer's disease, ischemic stroke, hippocampal stab injury, glioma, hypothalamus inflammation, and plays an important role in the development of the disease." (PMID 37422673, 2023). "Furthermore, SERPINA3 has also been identified as a specific biomarker of delirium and Alzheimer’s disease." (PMID 33260845, 2020). "Previous studies indicated that peripheral SERPINA3 levels are not elevated in patients with dementia, other than those with Alzheimer's disease, and increase as dementia progresses." (PMID 35095596, 2021).
breast carcinoma (22 papers, 2012 to 2026). "It was shown that increased expression of SERPINA3 in tissue from breast cancer patients was associated with stronger proliferation and increased viability of the tumour." (PMID 40087712, 2025). "In previous studies, SERPINA3 has been identified as an important diagnostic marker for various types of cancer, including liver cancer, breast cancer, and colorectal cancer (6-, 8)." (PMID 40367014, 2025). "Many studies have linked the observed increased expression levels of the SerpinA3 gene with its crucial role in several pathologies in various types of cancer, such as glioblastoma, breast cancer, colorectal cancer, and melanoma." (PMID 39062058, 2024). "All above results together suggest that the expression of SERPINA3 is negatively associated with endocrine resistance in ER+ breast cancer." (PMID 37414914, 2023). "According to data retrieved from cBioPortal, the expression of ESR1, which encoded ERα, and SERPINA3 were positively related in breast cancer, as evidenced by a Pearson correlation coefficient of 0.47." (PMID 37414914, 2023). "So far, overexpression of SERPINA3 has been observed in several cancer types including breast cancer and the high expression level has been demonstrated to positively correlate with poor prognosis in patients with breast cancer, which means SERPINA3 can be associated with a shorter OS." (PMID 33785008, 2021). "Recent studies have confirmed that SERPINA3 have the potential to promote tumor invasion and migration, epithelial-mesenchymal-transition in breast cancer, hepatocellular carcinoma and lung cancer." (PMID 41550507, 2026). "Increased levels of both circulating and tissue-derived SERPINA3 have been described in leukaemia; lymphoma and breast cancer patients, compared to healthy controls." (PMID 40087712, 2025). "In breast cancer tissue, SERPINA3 was also found upregulated, and it seems to promote cell proliferation, migration, and invasion." (PMID 40087712, 2025). "We observed a significant difference in SERPINA3 values according to sex, cancer type (breast cancer vs haematological malignancies), anthracycline type and the use of radiotherapy." (PMID 40087712, 2025). "The enhanced expression of SerpinA3 has been shown to promote tumor cell invasion and migration in colon cancer, breast cancer, and glioblastoma cell lines." (PMID 38279150, 2024). "In conclusion, the bioinformatic and experimental analyses suggest that ANKRD11 works downstream of ERα-SERPINA3 pathway to promote estrogen-deprivation-resistance (AI resistance) in ER+ breast cancer." (PMID 37414914, 2023). "Microarray data of pre- and post-AI therapied breast tumors in GSE105777 and GSE153470 showed diminished expression of SERPINA3 in breast cancer patient samples after AI treatment 39,40." (PMID 37414914, 2023). "Many studies have shown increased expression levels of the SERPINA3 gene in various types of cancer, such as glioblastoma, colorectal cancer, endometrial cancer, breast cancer, or melanoma." (PMID 36672665, 2023). "In conclusion, these data jointly suggest the contribution of decreased SERPINA3 to AI-resistance in ER+ breast cancer." (PMID 37414914, 2023). "SERPINA3 is a direct target gene of estrogen receptor and contributes to aromatase inhibitor resistance in breast cancer cells through an ANKRD11-HDAC3 pathway." (PMID 37414914, 2023). "To determine the molecules working downstream of SERPINA3 in inducing AI resistance, we first identified 61 genes whose expressions are negatively correlated with SERPINA3 in breast cancer by using the cBioPortal database." (PMID 37414914, 2023). "In glioblastoma and breast cancer, high expression of SERPINA3 is closely related to cancer cell proliferation, invasion, migration, and epithelial-mesenchymal transition, and thus leads to poor prognosis and tumor recurrence." (PMID 36406134, 2022). "Based on the results, it seemed that IL17B, NFKBIE and SERPINA3 mainly prompted the development of breast cancer." (PMID 33785008, 2021).
breast carcinoma (continued). "Thereby effectively reducing the expression of SERPINA3, offering a promising therapeutic strategy for the treatment of aggressive breast cancer cells." (PMID 33569740, 2021). "The upregulation of SERPINA3 has been reported in some cancer types, including endometrial carcinoma, lung carcinoma, colon carcinoma, breast carcinoma, and melanoma." (PMID 31998645, 2019). "Plasma SERPINA3 concentrations were significantly elevated in breast cancer patients 24 h post-DOX." (PMID 41754775, 2026). "Specifically, Tamoxifen upregulated SERPINA3 and IGLV7-43, while Anastrozole-treated T47Ds downregulated IGCL3 which is indicated by the Human Protein Atlas as being associated with favourable outcome in breast cancer." (PMID 38233507, 2024). "SERPINA3 is expressed at higher level in epithelial cells of BRCA1 and BRCA2 mutation carriers compared with non-carrier; this has previously been shown to confer invasiveness and epithelial-to-mesenchymal transition (EMT) phenotype to breast cancer cells." (PMID 38059556, 2024). "More importantly, our findings suggest that decreased SERPINA3 as well as increased ANKRD11 expression as biomarkers that may predict the efficiency of HDAC3 inhibitor in treating AI-resistant breast cancer." (PMID 37414914, 2023). "By utilizing the two AI-resistant cell model MCF-7 LTED and T47D LTED, we revealed that downregulated expression of SERPINA3, an ERα target gene, confers endocrine-resistance to breast cancer cells during AI therapy by enhancing ANKRD11 expression and HDAC3 deacetylase activity." (PMID 37414914, 2023). "While most studies demonstrated a positive role for SERPINA3 in tumor progression, our findings showed that SERPINA3-deficiency promotes AI resistance in ER+ breast cancer, suggesting a negative role of SERPINA3 in hormone therapy resistance induction." (PMID 37414914, 2023). "Moreover, SERPINA3 expression was significantly higher in ER+ than ER− breast cancer, which also demonstrated a positive correlation between ER pathway and SERPINA3 expression." (PMID 37414914, 2023). "This also implied that SERPINA3 may have a certain effect on cisplatin resistance of breast cancer cells, which need more efforts to go a step further to verify." (PMID 33569740, 2021). "Overexpression of another member gene SERPINA3 is also reported to promote tumor invasion and EMT in breast cancer." (PMID 40033360, 2025). "ATF3-transgenic mice with orthotopic breast cancer, which showed enhanced tumor growth, exhibited increased cardiac expression of periostin, CTGF, FN, SerpinA3, and CP." (PMID 38279150, 2024). "However, the biological function of SERPINA3 in breast cancer (BC) remains unclear." (PMID 33569740, 2021). "In this study, SERPINA3 was identified to be a direct target gene of ERα, and its downregulation enhanced the expression of ankyrin repeat domain containing 11 (ANKRD11), which resulted in elevated HDAC3 activity and AI resistance in ER+ breast cancer." (PMID 37414914, 2023). "The nuclear translocation of SERPINA3 during anti-estrogen therapy and the resulted benign prognostic effect make sense of the negative role of SERPINA3 in AI resistance development in ER+ breast cancer." (PMID 37414914, 2023). "Furthermore, according to the data retrieved from TCGA database, lower expression of SERPINA3 is specifically correlated with poorer prognosis in both luminal A and luminal B subtypes of ER+ breast cancer, but not ER- subtype." (PMID 37414914, 2023). "Higher SERPINA3 values were observed in males vs females, haematological cancers vs breast cancer and in HER2 positive vs HER2 negative breast cancer." (PMID 40087712, 2025).